FSTL1 (follistatin like 1)
Diseases named in the same sentence as FSTL1 in open-access papers (continued):
Sharing a sentence is not in itself a finding about the gene and the disease.
coronary artery disease (7 papers, 2016 to 2025). "This study is derived from the medical specialty thesis titled “The Association Between FABP4, Adiponectin, Irisin, and FSTL1 Levels and Metabolic Syndrome in Coronary Artery Disease” completed by Dr. Uyaner Kan under the supervision of Dr. Kilinc." (PMID 41187309, 2025). "Depending on its glycosylation state, Follistatin-like 1 (FSTL1) has been shown to increase cardiomyocyte (CM) proliferation, decrease CM apoptosis, and prevent cardiac rupture in animal models of ischemic heart disease." (PMID 35317048, 2022). "In ischemic heart disease, FSTL1 prevents myocytes apoptosis through inhibiting BMP4-p-Smad1/5/8 signaling and enhancing AMPK pathway." (PMID 28852126, 2017). "We have shown that Fstl1 acts as an anti-inflammatory factor that protects against ischemic heart disease and chronic kidney disease." (PMID 27145224, 2016).
glioblastoma (7 papers, 2009 to 2025). The most malignant astrocytic tumor (WHO grade IV). "The Fstl1/DIP2A/MGMT pathway is linked to temozolomide resistance in glioblastoma, with increased Fstl1 expression contributing to resistance, while decreased expression enhances drug sensitivity." (PMID 40781854, 2025). "For instance, FSTL1 overexpression has been associated with poor prognosis of glioblastoma, progression of prostate cancer and bone metastasis." (PMID 30131854, 2018). "Recently, researchers have reported that FSTL1 up-regulates the BMP4-Smad signaling in lung adenocarcinoma, while in glioblastoma, FSTL1 down-regulates the same signaling." (PMID 36756161, 2023). "Fstl1, a glycoprotein highly expressed in glioblastoma, competitively binds DIP2A to block DIP2A nuclear translocation, so as to hinder DIP2A from binding the HDAC2–DMAP1 complex." (PMID 30542120, 2019). "FSTL1 was found to be downregulated in v-myc and v-ras oncogene-transformed cells, with a possible role in carcinogenesis, poor prognosis of glioblastoma, and progression of prostate cancer." (PMID 28800781, 2017). "FSTL1 upregulation was also observed in glioblastoma and was correlated with poor prognosis in glioblastoma patients." (PMID 28852126, 2017). "We found FSTL1 transcripts in brain capillaries and over expressed in glioblastoma samples." (PMID 19924294, 2009). "Importantly, PRCP, PTRF, LIMS1 and FSTL1 were expressed in the developing murine brain vasculature and are also overexpressed in glioblastoma, suggesting a role in tumor angiogenesis." (PMID 19924294, 2009).
Hypertension (7 papers, 2011 to 2025). The presence of chronic increased pressure in the systemic arterial system. "In multivariable logistic regression analyses, circulating levels of adiponectin and FSTL1 remained significantly associated with the presence of metabolic syndrome after adjusting sequentially for age, waist circumference, hypertension, glucose, triglycerides, and HDL levels." (PMID 41187309, 2025).
melanoma (7 papers, 2009 to 2025). A malignant, usually aggressive tumor composed of atypical, neoplastic melanocytes. "In a recent study, FSTL1 was downregulated in the lung tissues of mice exposed to intermittent hypoxia (IH) and inoculated with melanoma cells, suggesting a possible involvement of FSTL1 in IH-induced tumor lung metastasis." (PMID 41458545, 2025). "Downregulation of FSTL1 in human melanoma cells using a siRNA results in the inhibition of the expression of genes associated with migration, such as CCL2 and CXCL12, and with the formation of bone metastasis, such as CCR2 and CXCR4." (PMID 29594389, 2018). "Notably, FSTL1 showed positive correlations with M2 macrophages in primary melanoma, aligning with prior studies that link it to M2 polarization in other cancers." (PMID 40943183, 2025). "Linear correlation and statistical significance (p < 0.05) between ZEB1 and FSTL1 were observed in cervical cancer (CESC), esophageal cancer (ESCA), head and neck cancer (HNSC), lung squamous cell carcinoma (LUSC), melanoma (SKCM), and sun-exposed/unexposed skin." (PMID 38605354, 2024).
nasopharyngeal carcinoma (7 papers, 2016 to 2024). A carcinoma arising from the nasopharyngeal epithelium. "In summary, FSTL1 in CC shows a similar carcinogenesis suppressor function as in ovarian, renal, lung, and nasopharyngeal cancers." (PMID 36756161, 2023). "Recently, more and more works have identified the potential of FSTL1 as a tumor suppressor because of its ability to negatively regulate the motility and invasion of ovarian, renal, lung, and nasopharyngeal cancer cells." (PMID 36756161, 2023). "FSTL1 was found to strengthen the antigen presentation ability of drendritic cell by activating NF-κb pathway in nasopharyngeal carcinoma." (PMID 34112144, 2021). "This candidate tumor suppressor, FSTL1, has also been shown to mediate tumor immune evasion in nasopharyngeal cancer through hyper-methylation silencing." (PMID 31356589, 2019). "Moreover, in nasopharyngeal carcinoma, FSTL1 blocks Wnt7a inhibition of ERK phosphorylation, inducing MMP9 production, extracellular matrix degradation, and metastasis." (PMID 38605354, 2024). "Compared to healthy tissue, the expression level of FSTL1 was found to be reduced in biopsies of various types of cancers, such as prostate, ovarian, endometrial, kidney, nasopharyngeal carcinoma (NPC), and lung adenocarcinoma." (PMID 29594389, 2018). "Interestingly, in nasopharyngeal carcinoma (NPC) cell lines and tumour biopsies, decreased levels of FSTL1 mRNA correlate with hypermethylation of CpG islands in its proximal promoter (− 166 to + 332 bp) and also with increased tumourigenicity." (PMID 29594389, 2018).
osteoarthritis (7 papers, 2011 to 2025). A noninflammatory degenerative joint disease occurring chiefly in older persons, characterized by degeneration of the articular cartilage, hypertrophy of bone at the margins and changes in the synovial membrane. "In the present study, chondrocytes stimulated with IL-1β exhibited downregulation of COL2A1 and upregulation of MMP13, Prg4, Sulf1, Adam10, and Fstl1, supporting that enhanced inflammation is a critical mechanism underlying the progression of osteoarthritis." (PMID 37525533, 2023). "Our previous work has revealed that expression of follistatin-like protein 1 (FSTL1) is elevated in the synovial tissues from osteoarthritis (OA) patients." (PMID 25888873, 2015). "The aim of this study is to detect FSTL1 expression and to further assess its potential utility as a biomarker of joint damage in osteoarthritis (OA) patients." (PMID 22117761, 2011). "FSTL1 activates NFκB signaling in HEK293 cell line, and functions as an important pro-inflammatory factor in the pathogenesis of osteoarthritis by activating the canonical NFκB pathway and enhancing synoviocyte proliferation." (PMID 28498809, 2017).
respiratory failure (7 papers, 2016 to 2021). The significant impairment of gas exchange within the lungs resulting in hypoxia, hypercarbia, or both, to the extent that organ tissue perfusion is severely compromised. "We have previously generated Fstl1-deficient mice and observed the postnatal lethality as a result of respiratory failure." (PMID 27355685, 2016). "As an antagonist of the BMP4 signaling pathway, FSTL1 plays a crucial part in the embryogenesis of lung and alveolar, thus FSTL1−/− mice showed postnatal lethality due to respiratory failure." (PMID 33509151, 2021). "Homozygous Fstl1−/− mice die of respiratory failure shortly after birth, so Fstl1+/− or conditional knockout mice have been used to study the lung and kidney fibrosis." (PMID 32933544, 2020). "Deletion of Fstl1 in mice led to postnatal death as a result of respiratory failure due to multiple defects in lung development." (PMID 28574994, 2017). "FSTL-1 gene-knockout (KO) mouse pups die of respiratory failure soon after birth." (PMID 33936382, 2021). "Deletion of Fstl1 leads to postnatal death in mice due to respiratory failure." (PMID 27355685, 2016).
Insulin resistance (6 papers, 2013 to 2026). Increased resistance towards insulin, that is, diminished effectiveness of insulin in reducing blood glucose levels. "Clinical and population-based studies have linked circulating FSTL1 to metabolic syndrome and insulin resistance, suggesting that it is regulated by metabolic status." (PMID 41602834, 2026). "It was previously confirmed that FSTL1 is associated with insulin resistance and that circulating FSTL1 levels were elevated in patients with T2DM." (PMID 34957094, 2021). "FSTL1 was also implicated in the regulation of insulin resistance and circulating FSTL1 levels were elevated in patients with T2DM." (PMID 34957094, 2021). "Given the causative role of inflammation in insulin resistance, we further examined the impact of FSTL1 on insulin signaling in adipocytes." (PMID 24347831, 2013). "For instance, correlation analysis between FSTL1 expression in adipose tissue and the development of insulin resistance in ob/ob mice may provide evidence for its implication in insulin resistance." (PMID 24347831, 2013). "However, further research is required to elucidate the role of FSTL1 in the development of inflammation and insulin resistance in vivo." (PMID 24347831, 2013). "In addition, adenovirus-mediated overexpression of FSTL1 or blocking its actions through neutralizing antibodies in mice, as used in previous studies, will more directly elucidate the role of FSTL1 in the pathogenesis of insulin resistance." (PMID 24347831, 2013). "Follistatin-like protein 1 (FSTL1) is a cardiokine with proven benefits in multiple pathological processes including cardiac fibrosis and insulin resistance." (PMID 34957094, 2021). "Follistatin-like protein-1 (FSTL-1) is an adipomyokine that could be a potential regulator of glucose metabolism and insulin resistance in T2DM." (PMID 33923652, 2021).
myocardial ischemia (6 papers, 2017 to 2025). A disorder of cardiac function caused by insufficient blood flow to the muscle tissue of the heart. "The cardioprotective effect of FSTL1 has been extensively studied in recent years, but its role in myocardial ischemia/reperfusion injury (IRI) is unclear." (PMID 31139662, 2019). "Second, ACS patients were excluded since severe myocardial ischemia and enhanced inflammation might significantly influence FSTL1 levels." (PMID 36684598, 2022). "Additionally, recently the effect of FSTL1 injections in cardiac ischemia has been actively studied on the ability to regenerate myocardial cells." (PMID 34440203, 2021). "In a report, follistatin-like 1 (FSTL1) in the epicardium induced cell cycle re-entry of cardiomyocyte and protected the heart function from myocardial ischemia injury." (PMID 35006441, 2021).
prostate carcinoma (6 papers, 2017 to 2025). A carcinoma that arises from epithelial cells of the prostate gland. "Another family member, FSTL1 is associated with reduced levels in prostate cancer; FSTL1 expression correlates with inflammatory factors and transforming factors." (PMID 34425560, 2021). "The expression of FSTL1 is reduced in various types of cancer, such as cancer of the prostate, ovary, endometrium, pancreas, kidney, nasopharyngeal carcinoma and lung adenocarcinoma in comparison with healthy tissue." (PMID 34440203, 2021).
coronary artery aneurysms (5 papers, 2012 to 2025). "The current study was designed to determine if plasma levels of FSTL-1 correlate with the development of Kawasaki Disease and development of coronary artery aneurysms." (PMID 22817878, 2012). "The highest levels of FSTL-1 were observed in patients who developed coronary aneurysms (mean 225.5 ng/ml, p=0.005 compared to the acute time point )." (PMID 22817878, 2012). "Plasma levels of follistatin-like protein 1 (FSTL-1), a proinflammatory protein produced by mesenchymal tissue including cardiac myocytes was shown to be elevated in patients with acute KD and may correlate with the development of coronary artery aneurysms." (PMID 27643389, 2014). "Additionally, since FSTL-1 is produced by cardiac myocytes, these results suggest a possible role for FSTL-1 in the formation of coronary artery aneurysms." (PMID 22817878, 2012).
pulmonary hypertension (5 papers, 2017 to 2025). Increased pressure within the pulmonary circulation due to lung or heart disorder. "Studies have indicatedthat FSTL1 can promote tissue remodeling in cases of cardiovascular injury.Patients with COPD-associated pulmonary hypertension and mouse models ofhypoxia-induced pulmonary hypertension exhibited elevated serum FSTL1 levels." (PMID 39077334, 2024). "Serum levels of Fstl1 are elevated in human patients with pulmonary hypertension related to COPD, and in the lungs of hypoxic mice with high right ventricular systolic pressure (RVSP) and RVH." (PMID 36388115, 2022). "The precise mechanisms that Fstl1 regulates ASM and VSM formation, if and how Fstl1 regulates some important signaling pathways, such as BMP, SHH, WNT and FGF, during lung SM development and SM-related lung diseases including pulmonary artery hypertension, are actively pursued in our laboratories." (PMID 28574994, 2017).
renal fibrosis (5 papers, 2016 to 2025). A final common manifestation of a wide variety of chronic kidney diseases characterized by glomerulosclerosis and tubulointerstitial fibrosis. "Through immunohistochemistry, H&E, and sirius red staining, we also observed a marked increase of FSTL1 concurrent with the progression of renal fibrosis induced by UUO." (PMID 39990230, 2025). "Renal fibrosis was significantly ameliorated in mice treated with Ad-Fstl1 compared with those receiving Ad-CTL, as indicated by the reduced mRNA and protein expression of major ECM components, such as collagen I and fibronectin." (PMID 39990230, 2025). "In future studies, we will utilize cell-specific Fstl1 knockout mice, combined with RNA sequencing, to further investigate these and other signaling pathways involved in the pathogenesis of renal fibrosis." (PMID 39990230, 2025). "Consequently, FSTL1 exerts a predominant anti-fibrotic effect in the progression of UUO-induced renal fibrosis." (PMID 39990230, 2025). "This study further provides evidence that upregulation of FSTL1 may be beneficial in the treatment of renal fibrosis in which inflammation plays a central role." (PMID 39990230, 2025). "Among the genes predicted to be regulated by p300 in proximal tubule cells during renal fibrosis, we selected the POSTN, FSTL1, and FSCN1 genes, as these encode secreted proteins that mediate interactions with surrounding cells and affect the mesenchymal transition." (PMID 40588562, 2025). "Clinical and basic research have confirmed that FSTL1 is upregulated in patients with chronic kidney disease and is involved in promoting renal fibrosis, inflammation, and cellular apoptosis processes.This is consistent with our results of urine from DN patients." (PMID 38951833, 2024). "FSTL1 promotes the Wnt/β-catenin signaling pathway and thus aggravates renal fibrosis." (PMID 35525270, 2022). "Masson’s trichrome staining revealed that renal fibrosis was aggravated by FSTL1." (PMID 35525270, 2022). "Importantly, Fstl1+/- mice exhibited more severe renal fibrosis." (PMID 39990230, 2025). "However, the role of FSTL1 in renal fibrosis remains inconsistent." (PMID 39990230, 2025). "ATAC-sequencing analysis of PTCs from an ischemia-reperfusion injury-induced renal fibrosis mouse model (GSE197815) revealed increased chromatin accessibility in the promoter regions of POSTN, FSTL1, and FSCN1 genes during the progression of renal fibrosis." (PMID 40588562, 2025). "Nevertheless, our current in vivo and in vitro studies demonstrate that FSTL1, derived from renal tubular epithelial cells, inhibits NF-κB-mediated signaling, ultimately mitigating UUO-induced renal fibrosis." (PMID 39990230, 2025). "Interestingly, increased p300 in proximal tubular cells (PTCs) promoted renal fibrosis development by mediating the endothelial to mesenchymal transition (EndMT) via upregulation of the mesenchymal-transition-related secreted proteins POSTN, FSTL1, and FSCN1." (PMID 40588562, 2025). "Based on our demonstration that p300 promotes the secretion of POSTN, FSTL1, and FSCN1 in renal proximal tubule cells, thereby increasing the EndMT, we next investigated whether selective inhibition of p300 suppressed the secretion of these three proteins in a UUO-induced renal fibrosis mouse model." (PMID 40588562, 2025). "We also examined FSTL1 expression in kidneys from patients with immunoglobulin A nephropathy at grade III, or membranous nephropathy at grade II, which had developed renal fibrosis (data not shown), and found colocalization of FSTL1 with PDGFRβ." (PMID 35525270, 2022).
autoimmune disease (4 papers, 2017 to 2022). A disorder resulting from loss of function or tissue destruction of an organ or multiple organs, arising from humoral or cellular immune responses of the individual to their own tissue constituents. "In recent years, a number of published reports have identified a new role for FSTL1 in the regulation of immune cell function, demonstrating overexpression of FSTL1 in several autoimmune diseases." (PMID 36143013, 2022). "The protein follistatin-like 1 (FSTL1), also known as transforming growth factor-stimulated clone 36 (TSC-36) or follistatin-related protein (FRP), is a soluble secreted extracellular glycoprotein that plays an important role in many kinds of tissue degeneration and autoimmune diseases." (PMID 33936382, 2021).
chronic kidney disease (4 papers, 2016 to 2024). Impairment of the renal function secondary to chronic kidney damage persisting for three or more months. "Again, FSTL1 is not the only ligand to increase expression of these genes in vivo, but we were able to see strong correlations between Fstl1 mRNA levels and the mRNA levels of Ccl2 and Tnfa, two cytokines implicated in the progression of chronic kidney disease." (PMID 34502419, 2021). "Pathology studies have shown that tubular atrophy and cell loss are features of chronic kidney disease but a role for FSTL1 in apoptosis in the kidney is unknown." (PMID 34502419, 2021). "FSTL1 promotes wound healing by virtue of its effects on fibrosis, analogous to the role we think that it plays in chronic kidney disease." (PMID 34502419, 2021). "We extended our studies of Fstl1 and its receptors Tlr4 and Dip2a in another experimental model of chronic kidney disease: murine UUO." (PMID 34502419, 2021). "In conclusion, our studies show that FSTL1 is a fibroblast-derived cytokine expressed in the kidney and up-regulated in both experimental and clinical chronic kidney disease." (PMID 34502419, 2021). "This work supports our notion that FSTL1 could function as a paracrine factor in the kidney to affect the progression of chronic kidney disease by engaging Tlr4 receptors on kidney tubular cells." (PMID 34502419, 2021). "FSTL1 may be a new treatment target in chronic kidney disease." (PMID 34502419, 2021). "Among them, FSTL1 has been proved to promote the progression of focal segmental glomerular sclerosis(FSGS), membranous nephropathy (MN), immunoglobulin A (IgA) nephropathy (IgAN), and other chronic kidney diseases." (PMID 38390317, 2024).
Kawasaki disease (4 papers, 2012 to 2025). A rare inflammatory disease characterized by an acute febrile, systemic, self-limiting, medium-vessel vasculitis primarily affecting children. "FSTL-1 levels were significantly elevated in patients with acute Kawasaki Disease as compared to age-matched controls (mean 161.7 ng/ml vs. 121.3 ng/ml, p<0.001)." (PMID 22817878, 2012). "Plasma levels of FSTL-1 are elevated in acute Kawasaki Disease." (PMID 22817878, 2012).